IGF2BP3 (insulin like growth factor 2 mRNA binding protein 3)
Diseases named in the same sentence as IGF2BP3 in open-access papers (continued):
Sharing a sentence is not in itself a finding about the gene and the disease.
bladder cancer (continued). "Our study revealed that palbociclib possesses the ability to overcome cisplatin resistance and suppress proliferation of bladder cancer cells characterized by elevated levels of IGF2BP3 protein expression." (PMID 40083693, 2025). "Our findings demonstrated that IGF2BP3 enhances resistance to cisplatin in bladder cancer cells by interacting with CDK6, thereby impeding the cytotoxic effects of cisplatin." (PMID 40083693, 2025). "This study demonstrates that Insulin-like growth factor 2 mRNA binding protein 3 (IGF2BP3) promotes bladder cancer (BCa) proliferation and chemoresistance in an m6A-dependent manner by directly stabilizing Cyclin-dependent Kinase 6 (CDK6) mRNA." (PMID 40959282, 2025). "In our study, we conducted a comprehensive investigation into the landscape of m6A modification in bladder cancer and identified a distinct expression pattern of IGF2BP3 in this context." (PMID 40083693, 2025). "Then, we performed WB experiments on bladder cancer cell lines with knockdown or overexpression of IGF2BP3 to investigate the expression changes of multiple cyclin proteins CDK2, CDK4, CDK6, and CCND1." (PMID 40083693, 2025). "Together, we confirmed that CDK6 interference decreased the cell proliferation and cisplatin resistance induced by IGF2BP3 in bladder cancer cells." (PMID 40083693, 2025). "We supplemented the medium of over-expressing IGF2BP3 or its control bladder cancer cells with 1μM palbociclib." (PMID 40083693, 2025). "To further elucidate the role of IGF2BP3 in bladder cancer proliferation and chemotherapy sensitivity, we stably transfected T24 and UMUC3 bladder cancer cells with lentivirus knockout, lentivirus overexpression, or control lentivirus constructs." (PMID 40083693, 2025). "CCK-8 assay results showed that knockdown of CDK6 reversed IGF2BP3 induced proliferation in bladder cancer cells." (PMID 40083693, 2025). "Conversely, the proportion of apoptosis of bladder cancer cells overexpressing IGF2BP3 was significantly reduced, further confirming that IGF2BP3 knockdown can increase the sensitivity of bladder cancer to cisplatin chemotherapy." (PMID 40083693, 2025). "Subsequently, our investigation on self-collected bladder cancer samples confirmed the overexpression of IGF2BP3 in tumor tissues." (PMID 40083693, 2025). "Further analysis based on the TMA cohort also found that bladder cancer patients with high expression of IGF2BP3 had poorer survival expectations (P=0.014)." (PMID 40083693, 2025). "IGF2BP3 expression was also upregulated in seven bladder cancer cell lines compared to SV-HUC-1 (human ureteral epithelial immortalized cell line)." (PMID 40083693, 2025). "Conversely, overexpression of IGF2BP3 augmented their proliferative ability of bladder cancer cells." (PMID 40083693, 2025). "In vitro experiments further corroborated the promotion of bladder cancer cell proliferation by IGF2BP3, as well as its contribution to cisplatin resistance." (PMID 40083693, 2025). "Future research, clinical trials are essential to assess the feasibility and clinical applicability of IGF2BP3-targeted therapies in bladder cancer treatment." (PMID 40083693, 2025). "Our in vivo and in vitro experiments identified IGF2BP3 as a key regulator of cisplatin resistance in bladder cancer." (PMID 40083693, 2025). "Meanwhile, flow cytometry showed that after cisplatin treatment, the apoptosis rate of IGF2BP3 knockdown bladder cancer cells increased significantly." (PMID 40083693, 2025). "In this study, we initially identified aberrant regulation of IGF2BP3 in bladder cancer through high-throughput sequencing data analysis." (PMID 40083693, 2025). "According to the IHC score, 152 patients with bladder cancer were divided into 102 patients with low IGF2BP3 expression and 50 patients with high IGF2BP3 expression." (PMID 40083693, 2025). "EDU assay was employed to assess DNA replication capacity in bladder cancer cells following either knockdown or overexpression of IGF2BP3." (PMID 40083693, 2025).
bladder cancer (continued). "In conclusion, our study underscores the pivotal role of IGF2BP3 in driving cisplatin resistance in bladder cancer, primarily by stabilizing CDK6 mRNA in an m6A-dependent manner." (PMID 40083693, 2025). "Taken together, IGF2BP3 was up-regulated in bladder cancer and predicted poor prognosis of bladder cancer patients." (PMID 40083693, 2025). "Combined with the results that high IGF2BP3 levels correlate with higher T stage, these findings suggest that bladder cancer with high IGF2BP3 levels exhibits fast cell proliferation." (PMID 38504159, 2024). "This study investigates the significance of IGF2BP3 in bladder cancer from both clinical and biological perspectives." (PMID 38504159, 2024). "Collectively, the study unveils that IGF2BP3-mediated SRD5A3 m6A modification facilitates bladder cancer progression and induces CDDP resistance, providing rational therapeutic targets for bladder cancer patients." (PMID 39680264, 2024). "We further assessed the correlation between IGF2BP3 expression levels and the clinicopathological features of bladder cancer using multiple datasets." (PMID 38504159, 2024). "Examination of E-MTAB-4321 dataset, which consisted of 476 early-stage bladder cancer, revealed that tumors exhibiting elevated IGF2BP3 levels had a higher tendency to progress to advanced T stage (p < 0.001)." (PMID 38504159, 2024). "Overall, our findings support the notion that IGF2BP3 promotes the progression of bladder cancer by affecting cell proliferation, EMT phenotype, and invasive behavior." (PMID 38504159, 2024). "To determine the pathways associated with IGF2BP3 expression in bladder cancer, we utilized Gene Set Enrichment Analysis (GSEA) to identify gene sets that exhibited enrichment or depletion in tumors with high IGF2BP3 expression." (PMID 38504159, 2024). "We observed a significant elevation in IGF2BP3 levels within bladder cancer samples, correlating with more advanced stages and grades, as well as an unfavorable prognosis." (PMID 38504159, 2024). "Functionally, the upregulation of IGF2BP3 expression exacerbated bladder cancer progression, including the proliferation, migration, and invasion of bladder cancer." (PMID 38504159, 2024). "Next, we intended to characterize the role of IGF2BP3 during cisplatin resistance development in bladder cancer." (PMID 39680264, 2024). "The following cellular and animal studies demonstrated that SRD5A3 and IGF2BP3 knockdown effectively reduced bladder cancer cell proliferation, prevented chemoresistance, and induced cell apoptosis." (PMID 39680264, 2024). "IGF2BP3 is overexpressed in bladder cancer tissue, and its high expression is closely related to poor prognosis in patients with bladder cancer." (PMID 39062595, 2024). "Given the involvement of HMGB1 in the inflammatory response, tumorigenesis, and allograft rejection, and its contribution to the progression of bladder cancer, we investigated the relationship between IGF2BP3 and HMGB1." (PMID 38504159, 2024). "Specifically, IGF2BP3 promotes the activation of the JAK/STAT pathway in bladder cancer cells, thereby promoting their proliferation." (PMID 39062595, 2024). "In this study, we sought to demonstrate the oncogenic role of SRD5A3 and its interplay with IGF2BP3 via a m6A-dependent manner in bladder cancer and CDDP resistance." (PMID 39680264, 2024). "Upon analyzing this data, it was discovered that the IGF2BP3 copy number was often amplified in bladder cancer of TCGA BLCA dataset." (PMID 38504159, 2024). "While it exhibited low expression in normal urothelial bladder samples, around 34% of high-grade bladder cancer samples showed high levels of IGF2BP3 protein, consistent with the mRNA data." (PMID 38504159, 2024). "Subsequently, we delved deeper into the mechanism behind the upregulation of IGF2BP3 in bladder cancer." (PMID 38504159, 2024).
bladder cancer (continued). "In the present study, we found that more than 45% of bladder cancer harbor copy number gain/amplification of IGF2BP3, and its copy number positively correlated with IGF2BP3 expression." (PMID 38504159, 2024). "In conclusion, the study provides compelling in vitro and in vivo evidences proving the m6A modification machinery between SRD5A3 and IGF2BP3 in bladder cancer." (PMID 39680264, 2024). "Subsequent investigations revealed that the upregulation of IGF2BP3 expression is triggered by copy number gain/amplification and promoter hypomethylation in various tumor types, including bladder cancer." (PMID 38504159, 2024). "To investigate the role of IGF2BP3 in promoting the progression of bladder cancer in vivo, we created xenograft models in BALB/c nude mice by implanting BFTC905 cells (control vs. IGF2BP3 knockdown)." (PMID 38504159, 2024). "High levels of IGF2BP3 were found to be correlated with higher N/M stages and invasion in bladder cancer." (PMID 38504159, 2024). "We stably transfected the bladder cancer cell lines RT112/84 with an IGF2BP3 expression lentivirus or a control lentivirus." (PMID 38504159, 2024). "In this study, we revealed the regulation of SRD5A3 mRNA expression mediated by m6A reader IGF2BP3 during cisplatin resistance development in bladder cancer." (PMID 39680264, 2024). "Through analyzing the RIP-seq dataset and GEO database,we identified UCA1 as an interaction partner of IGF2BP3, which was initially recognized as a promoter of bladder cancer." (PMID 38760723, 2024). "The study identified SRD5A3 as an oncogene for bladder cancer and stabilized by a m6A reader, IGF2BP3, to sustain CDDP resistance." (PMID 39680264, 2024). "In contrast to the positive regulation of gene copy number on IGF2BP3 expression, our current study provides evidence that promoter methylation serves as an inhibitory factor for IGF2BP3 expression in bladder cancer." (PMID 38504159, 2024). "Given the association of HMGB1 with the inflammatory response and immune microenvironment, our study aimed to explore the relationship between the IGF2BP3 level and the immune response in bladder cancer." (PMID 38504159, 2024). "We further reveal that IGF2BP3 enhances the advancement of bladder cancer by stabilizing the mRNA of HMGB1." (PMID 38504159, 2024). "Knocking down the expression of IGF2BP3 in bladder cancer can increase apoptosis and induce cell cycle arrest, implying that it originally promoted cell proliferation via inhibiting apoptosis and regulating cell cycle." (PMID 36831493, 2023). "IGF2BP3 overexpression was related to disease progression and poor prognosis, as well as infiltration of immune cells in bladder cancer." (PMID 36732736, 2023). "Based on the data of bio-informatics and experimental methods, IGF2BP3 is over-expressed in bladder cancer and was strongly correlated with patients’ survival prognosis." (PMID 37598390, 2023). "Silencing IGF2BP3 expression decreased the number of migrated and invaded bladder cancer cells while ectopic expression of IGF2BP3 significantly enhanced the migrated and invaded rate of bladder cancer cells." (PMID 36732736, 2023). "Our Cox regression analysis demonstrated that IGF2BP3 was independently prognostic for OS in bladder cancer." (PMID 36732736, 2023). "In the present study, we identified IGF2BP3 as a prognostic marker and promising therapeutic target in bladder cancer." (PMID 36732736, 2023). "We compared the data sets for low and high IGF2BP3 expression using GSEA to identify signaling pathways activated during bladder cancer." (PMID 36732736, 2023).
bladder cancer (continued). "For validation, we collected 95 bladder cancer samples and found that IGF2BP3 expression was higher in bladder cancer tissues than that in non-tumor bladder tissues by immunohistochemistry staining." (PMID 36732736, 2023). "IGF2BP3 plays an important role in the promotion of bladder cancer progression through fine particulate matter (PM2.5)." (PMID 37298373, 2023). "In bladder cancer, expression of IGF2BP3 was significantly upregulated in tumors compared to normal tissues, with a median level of 1.007 in tumor and 0.170 in normal tissue (p < 0.001)." (PMID 36732736, 2023). "Both IGF2BP3 and immune cell infiltration play critical roles in the development and progression of bladder cancer." (PMID 36732736, 2023). "We performed immunohistochemical staining for IGF2BP3 expression of formalin-fixed paraffin embedded primary bladder cancer of 95 patients who underwent resection at our institution." (PMID 36732736, 2023). "IGF2BP3 can be a promising independent prognostic biomarker and potential treatment target for bladder cancer." (PMID 36732736, 2023). "IGF2BP3 promotes migration and invasion of bladder cancer cells, while IGF2BP3 inhibition had the opposite effects." (PMID 36732736, 2023). "Our study found that IGF2BP3 expression in bladder cancer is correlated with the type and density of tumor-infiltrating immune cells." (PMID 36732736, 2023). "Our findings demonstrate that IGF2BP3 is overexpressed in bladder cancer and correlated with poor survival outcomes." (PMID 36732736, 2023). "The overall survival rate of bladder cancer patients with higher IGF2BP3 expression in tumors was significantly poorer than that of patients with lower IGF2BP3 expression in tumors (P = 0.024)." (PMID 36732736, 2023). "We found a positive correlation between the expression level of IGF2BP3 and the clinical stage of bladder cancer." (PMID 36732736, 2023). "Pan-cancer analyses reveal that IGF2BP3 was higher in most cancer types, including bladder cancer, and the same results were found in GSE3167." (PMID 36732736, 2023). "Next, we analyzed IGF2BP3 expression in one bladder cancer dataset (GSE3167, Platform: GPL96) retrieved from the GEO web database." (PMID 36732736, 2023). "In bladder cancer, immunohistochemistry staining analysis showed that there is a statistically significant correlation exists between IGF2BP3 expression and tumor staging." (PMID 36732736, 2023). "The protein level of IGF2BP3 was significantly elevated in bladder carcinoma samples compared with normal tissue." (PMID 36732736, 2023). "Wei Huang also reported that the abnormal activation of the JAK/STAT signaling pathway in bladder cancer induced by IGF2BP3, and the JAK/STAT signaling inhibitors markedly hindered the activity of IGF2BP3." (PMID 36376832, 2022). "In bladder cancer, IGF2BP3 was reported to enhance cell proliferation and inhibit cell apoptosis through activation of JAK/STAT pathway." (PMID 34312475, 2021). "Through an analysis of the TCGA database, we showed IGF2BP3 was up‐regulated in bladder cancer tissues, which was confirmed in experiments conducted with 5 pairs of bladder cancer tissues and bladder cancer cell lines." (PMID 33094561, 2020). "In order to confirm the role of IGF2BP3 in modulating tumour cell fate, IGF2BP3 was overexpressed or knocked down in bladder cancer cell lines." (PMID 33094561, 2020). "The role of IGF2BP3 in the cell cycle of bladder cancer cells was explored using flow cytometry assay." (PMID 33094561, 2020). "In this study, we explored the expression of IGF2BP3 in bladder cancer and subsequently investigated the prognostic and molecular function of IGF2BP3." (PMID 33094561, 2020). "Collectively, these results indicate that IGF2BP3 promotes the proliferative ability of bladder cancer cells." (PMID 33094561, 2020).
bladder cancer (continued). "The expression of IGF2BP3 in bladder cancer tissues was significantly higher than that in normal tissues (P = 0.0004); the means ± SD for IGF2BP3 expression in normal tissues and bladder cancer were 3.687 ± 0.258 and 6.195 ± 0.187, respectively." (PMID 33094561, 2020). "The effects of IGF2BP3 on the tumorigenicity of bladder cancer cells were also confirmed by in vivo assays." (PMID 33094561, 2020). "It is also conceivable that IGF2BP3 has a multi‐pathway interaction function in regulating cell physiology and tumorigenesis in bladder cancer, which requires future investigations." (PMID 33094561, 2020). "IGF2BP3 is a potential target for gene therapy of bladder cancer to make a better prognosis in the future." (PMID 33094561, 2020). "In summary, our study found IGF2BP3 up‐regulation exerted the positive biological role to promote the cell proliferation ability of bladder cancer cells in vitro and in vivo by modulating the JAK/STAT pathway." (PMID 33094561, 2020). "The OS rate of patients with bladder cancer with higher IGF2BP3 expression in tumours was significantly poorer than that of patients with lower IGF2BP3 expression in tumours (P = 0.0277)." (PMID 33094561, 2020). "Mechanistically, we revealed that IGF2BP3 promotes the activation of the JAK/STAT pathway in bladder cancer cells." (PMID 33094561, 2020). "Taken together, these results indicate that IGF2BP3 plays a vital role in the tumorigenicity of bladder cancer in vivo." (PMID 33094561, 2020). "Real‐time PCR and Western blotting showed higher IGF2BP3 in all four bladder cancer cell lines (5637, J82, T24 and UMUC3) compared to normal human bladder uroepithelium cell line (SV‐HUC‐1)." (PMID 33094561, 2020). "CCK-8 detection results showed that after cisplatin treatment, the sensitivity of bladder cancer cells in the IGF2BP3 knockdown group was significantly increased, while overexpression of IGF2BP3 significantly decreased the sensitivity of bladder cancer cells to cisplatin." (PMID 40083693, 2025). "Taken together, these results suggested that IGF2BP3 knockdown could increase cisplatin chemotherapy sensitivity of bladder cancer in vitro and in vivo." (PMID 40083693, 2025). "Moreover, IGF2BP3 promoted both the proliferation and cisplatin resistance of bladder cancer cells by binding to the 5'- UTR region of CDK6 mRNA and enhancing its stability in an m6A-dependent manner." (PMID 40083693, 2025). "Finally, our findings provided compelling evidence that the combined administration of CDK4/6-targeting inhibitors palbociclib and cisplatin effectively counteracted the oncogenic effects of IGF2BP3 and overcomes chemotherapy resistance in bladder cancer." (PMID 40083693, 2025). "Clinically, IGF2BP3 expression levels may serve as a valuable biomarker for predicting cisplatin resistance in bladder cancer patients, thereby facilitating the implementation of personalized treatment strategies." (PMID 40083693, 2025). "Furthermore, flow cytometry analysis revealed that knockdown of IGF2BP3 elevated the proportion of G1 phase cells in bladder cancer cells; on the contrary, overexpression of IGF2BP3 exhibited an opposite trend." (PMID 40083693, 2025). "We investigated whether IGF2BP3 regulated CDK6 expression by modulating the stability of CDK6 mRNA in bladder cancer cells." (PMID 40083693, 2025). "Indeed, the mRNA and protein expression of IGF2BP3 were significantly increased in tumor tissue compared with adjacent normal tissue of bladder cancer patients." (PMID 40083693, 2025). "Notably, CDK6 interference or treatment with the small molecule CDK6 inhibitor palbociclib effectively counteracted the pro-proliferative effect induced by IGF2BP3 while sensitizing bladder cancer cells to cisplatin." (PMID 40083693, 2025). "When we explored the sensitivity of chemotherapy, flow cytometry demonstrated that knockdown of CDK6 could significantly increase the apoptosis rate of bladder cancer cells reduced by IGF2BP3." (PMID 40083693, 2025).